CD4 (CD4 molecule)
Diseases named in the same sentence as CD4 in open-access papers (continued):
Sharing a sentence is not in itself a finding about the gene and the disease.
asthma (continued). "Therefore, we investigated the effects of EA on CD4+CD25+Foxp3+ Treg cells and the relationship between acupuncture mediated antiallergic effects and Treg-cell responses in a murine model of asthma." (PMID 22649477, 2012). "In conclusion, these results suggest that BUD is effective in controlling asthma inflammation by reducing both T lymphocyte survival and T lymphocyte co-stimulatory ICOS in CD4+/CD25− and by increasing the survival and the activities of CD4+/CD25+ cells." (PMID 23251336, 2012). "Conversely, treatment with CD4 control cells did not cause significant changes in Treg and Th1 cell frequency, while it increased Th2 cell numbers in the OVA-asthma mouse model." (PMID 22792275, 2012). "We therefore examined whether purified CD4 T cells (>98%) from patients with NAEB and asthma had higher levels of SOCS3 gene expression as consequence of the preferential development of Th2 cells." (PMID 21765854, 2011). "CD4+ T helper type 2 (TH2) cells, their cytokines IL-4, IL-5 and IL-13 and the transcription factor STAT6 are known to regulate various features of asthma including lung inflammation, mucus production and airway hyperreactivity and also drive alternative activation of macrophages (AAM)." (PMID 22014099, 2011). "The aim of this study was to assess differences in cytokine profile in peripheral CD4+ and CD8+ T cells between children with asthma and healthy controls and to determine whether increasing severity of asthma is related to cytokine production." (PMID 21197090, 2010). "In the present study, we provided evidence that increased frequency of CD4+/IL-13+, but not CD4+/IL-4+ T cells was correlated with severity of asthma and these findings further suggest that IL-13 is a principal cytokine responsible for asthmatic symptoms." (PMID 21197090, 2010). "Frequencies of CD4+ and CD8+ T cells producing IL-4, IL-13 after in vitro stimulation were significantly higher in asthma patients than in the control group (IL-4: P < .00001, P < .00003 for CD4+ and CD8+ T cells, resp., IL-13: P < .00001 for CD4+ and CD8+ T cells)." (PMID 21197090, 2010). "Recent findings in animal models have demonstrated that isocyanate-induced asthma does not always represent an IgE-mediated sensitization, but still a mixed profile of CD4+ Th1 and TH2, as well as a CD8+ immune response." (PMID 19036137, 2008). "In addition, there is correlation between the down regulation of CD4 and CD8 T-lymphocyte activation and the improvement in asthma control." (PMID 18315837, 2008). "With respect to pathogenesis, recent findings especially in animal models demonstrated that isocyanate-induced asthma does not always represent an IgE-mediated sensitization, but still a mixed profile of CD4+ Th1 and TH2, as well as CD8+ immune response." (PMID 19036137, 2008). "Surprisingly, there were no significant changes observed in the expression level of CD4 and CD8 markers, nor changes were found in CD4+/CD8+ ratio in the studied groups of asthma and HV." (PMID 19087256, 2008). "During asthma, self-reported African American (AA) patients exhibited higher IL2-STAT5 signaling, a key pathway in asthma pathophysiology, across bronchial and airway epithelium, circulating CD4+ T cells, whole blood, and peripheral blood mononuclear cells (PBMCs)." (PMID 42292854, 2026). "In an asthma mouse model, a mutant form of PD-L2 (K113S) lacking PD-1 interaction promotes Th1 polarization and suppresses Th2-mediated responses, acting as a costimulator for CD4+ T cell responses." (PMID 39860323, 2025). "Thus, we aimed to identify differential ILC, CD4+, and CD8+ T cell populations in blood between T2 and non‐T2 features in subjects with and without asthma, to elucidate mechanisms and ultimately improve diagnostics and treatment of common asthma endotypes." (PMID 40965120, 2025).
asthma (continued). "However, CD4+ T cells are well established as the principal drivers of allergic sensitization and asthma, whereas the involvement of CD8+ T cells has not been widely recognized." (PMID 41472747, 2025). "Based on our result that CST1 was significantly positively correlated with activated CD4 memory T cells, it can be inferred that blocking the expression of CST1 in the airway may prevent the development of asthma by inhibiting the activation of CD4 memory T cells." (PMID 36733482, 2023). "Although the high number of RBM CD4 + T-cells in ACO showed a statistical significance as compared to asthma, COPD-ES (P < 0.05), CS (P < 0.05), and NLFS (P < 0.05), it should be borne in mind that CD4 + T-cells in the RBM were noted only in 4 ACO patients, 1 asthma patients, and in 1 NLFS." (PMID 37700291, 2023). "The highest median proportion of PD-1 + CD4 + or PD-1 + CD8 + T cells were found in patients with ILD (83.1% [IQR 72.1; 87.5] and 73.8% [IQR 60.3; 86.3]) followed by patients with lung cancer (66.4% [IQR 59; 69] and 77.1% [IQR 35.8; 82.3]) and patients with asthma (61.3% [IQR 57.4; 70.5] and 57.3%)." (PMID 37535195, 2023). "Thus, iNKT cells express Acc1 and Fasn when they are stimulated, including in asthma, whereas conventional CD4+ and CD8+ T cells do not." (PMID 37917548, 2023). "Indeed, both former and current smokers had significantly higher frequencies of CD4+CD45RO+ILC3s in the blood than non-smoker asthma patients." (PMID 35789151, 2022). "Increases in CTLA-4 and TIM-3 expression not on CD8+ but CD4+ T cells, as well as an increase in Th17 cells, may reflect asthma-related inflammation activity." (PMID 35029177, 2022). "As group 2 innate lymphoid cells (ILC2s) were not markedly induced during the HDE/OVA model of asthma, we hypothesized that neutrophil depletion during sensitization enhanced the pathogenicity of conventional CD4+ T cells." (PMID 35191395, 2022). "It should be noted that smoking in the asthma group was also associated with slightly higher circulating ILC1 and CD45RO+ILC1 frequencies; however, it did not associate with higher CD4+CD45RO+ILC1 frequencies." (PMID 35789151, 2022). "Thus, unlike the equivalent subset in ILC3s, CD4+CD45RO+ILC1s are not specifically expanded in the blood of smoking patients with asthma." (PMID 35789151, 2022). "Recently, many studies have shown that Th2A cells characterized by CD3+ CD4+ HPGDS+ CRTH2+ CD161high ST2high CD49dhigh CD27low play a crucial role in allergic diseases, such as atopic dermatitis (AD), food allergy (FA), allergic rhinitis (AR), asthma, and eosinophilic esophagitis (EoE)." (PMID 36003397, 2022). "CD4+CD25high Treg cells from subjects with increased Ca2+ response showed increased pERK1/2 expression, whereas cells with poor Ca2+ response were from subjects without asthma." (PMID 34072455, 2021). "Decreased Th2 and increased Th17 response with higher TCR signal strength was observed in CerS2 null CD4+ T cells upon TCR stimulation and the severity of ovalbumin (OVA)-induced asthma was decreased in CerS2 null mice, implicating a pathological role of very-long-acyl chain SLs in asthma." (PMID 33800208, 2021). "Therefore, increasement of circulating CD4+CRTH2+CCR6+ memory Th2 cells may reflect the chronic airway allergic inflammation, an important immunological feature of asthma." (PMID 34090369, 2021). "Also, miR-15a, miR-15b, and miR-20a are downregulated in CD4+ T -cells from atopic pediatric patients with asthma in contrast to atopic and non-atopic subjects." (PMID 33673725, 2021). "Hi-C data in hematopoietic cells showed that two proxies of rs2589561 (r2 > 0.9) are located in a region that interacts with the GATA3 promoter in CD4+ T cells, suggesting that rs2589561 could function as a distal regulator of GATA3 in this asthma relevant cell type." (PMID 34669738, 2021).
asthma (continued). "In addition, the proportion of circulating CD4+CCR6+CRTh2+ memory Th2 cells were measured, and the wheezing children were followed up for 2 years to confirm whether they were diagnosed with asthma." (PMID 34090369, 2021). "While asthma involved pathways like NFAT in regulation of the immune response and other lymphocyte activation pathways including signaling through IL-4, IL-8, IL-3 and IL-9 in CD8+ cells, the most prominent pathway in CD4+ cells was VDR/RXR activation signaling." (PMID 32900903, 2020). "Patients with severe asthma possess more IFN-γ-positive and IL-17A-positive CD4-positive T cells in BAL cells and increased production of both IL-17A and IFN-γ by CD8-depleted PBMCs from patients with CS-resistant asthma compared with patients with CS-sensitive asthma." (PMID 30736433, 2019). "However, data from other studies indicate that the proportion of CCR4+ CD4+ T cells in peripheral blood or in the lungs does not always correlate with the severity of asthma." (PMID 29507584, 2018). "There were also some studies recognized that imbalance of Th1/Th2 does not fully account for the aetiology of asthma, and other CD4+ T cell subsets may be involved in asthma, including Th17 cells and regulatory T cells (Treg)." (PMID 29554934, 2018). "CD4+ T-cells may, therefore, contribute to the development and progression of asthma by providing sIL-6R to cells initially non-responsive to IL-6." (PMID 30534125, 2018). "The frequency of Foxp3+IL-10+ CD4+ T cells did not correlate with asthma severity (data not shown)." (PMID 29507584, 2018). "However, in these mice, infusion of Co-OVA asTregs was no longer able to suppress asthma, measured by both airway restriction and CD4+ T cell infiltration into the lung." (PMID 28638384, 2017). "The immunoregulatory index (CD4+/CD8+) in patients with asthma did not exceed 2.15 standard units." (PMID 27660519, 2016). "Three asthma-risk SNPs (rs4065275, rs8076131 and rs12603332) overlapped DHS in the first intron of ORMDL3; this ∼3.0 kb intronic region was also highly enriched for the H3K27ac mark, suggestive of active enhancer activity, in CD4+ T cells but not monocytes." (PMID 27848966, 2016). "It is important to acknowledge that the study, as conducted, does not cover all the aspects of asthma manifestation and it remains to be determined whether the transfer of WT CD4+ T cells is sufficient to reverse AHR and mucus production in PARP-1−/− mice." (PMID 26169874, 2015). "This imbalance may be important for development of airway obstruction in asthma as we found that decreased FEV1 correlated with the decreasing percentage of CD4+Foxp3+TGF-β+ cells and simultaneously with the increasing percentage numbers of CD4+IL-17+ cells." (PMID 25132806, 2014). "Our data confirm that existing IL-10-dependent mechanisms in atopic patients prone to development of asthma are not sufficient: These patients have lower numbers of CD4+ T cells positive for IL-10R, and in addition, their IL-10 levels drop following bronchial allergen challenge." (PMID 24865466, 2014). "In the absence of GILT, CD4-positive T cell responses to Der p 1 are significantly reduced, resulting in mitigated allergic airway inflammation in response to Der p 1 and house dust mite extracts in a murine model of asthma." (PMID 23326313, 2013). "Indeed, in a murine model of asthma, IL-22R1 is expressed in lung epithelial cells, but not in hematopoietic cells in the lung including alveolar macrophages, CD4+ T cells, and CD8+ T cells." (PMID 23577040, 2013). "Furthermore, careful comparison of the gene expression profiles of purified CD4+ T cells based on information from this study will further elucidate the molecular basis of the incidence and development of asthma with or without depression." (PMID 23110234, 2012).
asthma (continued). "Thus, the CD4+ T lymphocyte is emerging as a potentially attractive cell in which to seek novel insights into the pathogenesis of asthma with or without depression and to identify new therapeutic targets." (PMID 23110234, 2012). "Furthermore, NF-κB p50 plays a critical role in allergic sensitization and asthma; however, to our knowledge, Th2 differentiation of CD4+ T cells via NF-κB has not been described." (PMID 22347372, 2012). "Only a single Japanese study by Oneda demonstrates that in asthma dexamethasone induces cell apoptosis preferentially in T activated effector cells but no study has explored the effect of BUD in cell survival simultaneously in total lymphocytes, CD4+/CD25+ and CD4+/CD25− cells from asthmatics." (PMID 23251336, 2012). "In addition, most of those studies, including a clinical trial in human asthma (with the depleting anti-CD4 MAb keliximab), did not take advantage of non-depleting anti-CD4 MAbs." (PMID 21818308, 2011). "Adoptive transfer of sensitized L selectin+CD4+ T cells into naïve ELP-/- mice which post-OVA challenge, developed asthma, suggesting that L-selectin may be critically involved in the onset of Th2 response in asthma." (PMID 21835035, 2011). "It is to note that the role of CD4+CD25+ T cells could not be tested in the allergic asthma model since CD28−/− mice do not develop OVA-induced asthma." (PMID 20628601, 2010). "Moreover, by constructing a mouse model of HDM-induced asthma and a co-culture system of bone marrow dendritic cells (BMDCs) and T cells, we comprehensively analyze the role of TFEB in the process of antigen presentation by DCs and in mediating the immune response of CD4 + T cells." (PMID 38664707, 2024). "However, the relationship between asthma and CD4 gene has not been reported." (PMID 34285702, 2021). "Thus, ORMDL3 expression in CD4+ cells may be very important for enhancing Th2 responses in childhood asthma but may not be the key cell expressing ORMDL3, implicating it in the onset of asthma in childhood." (PMID 33661765, 2021). "Finally CD4+ lymphocytes stimulated with hemagglutinin (n = 139, p = .01), although this stimulation may not be representative of asthma biology." (PMID 31992292, 2020). "In addition to miRNAs, long non-coding RNAs (lncRNAs), which comprise 200 nucleotides lacking putative open reading frames, may regulate CD4+ T cell differentiation in asthma." (PMID 31231429, 2019). "However, to our knowledge, there is no report on lncRNA expression in CD4+ T cells in asthma." (PMID 31231429, 2019). "Interestingly, one recent study demonstrated that the numbers of TH1-enriched CD4-positive T cells in BAL cells was inversely correlated with the percent predicted forced expiratory volume in 1 s (FEV1), indicating the unique role of TH1 inflammation in severe asthma." (PMID 30736433, 2019). "However, the Th1 master transcription factor T-bet and the Th2 master transcription factor Gata3 were comparable in CD4+ T cells from both control and asthma mice, suggesting that Th2 differentiation in asthma may be independent of Gata3." (PMID 31231429, 2019). "We previously confirmed that the maintenance of Treg cell numbers in asthma patients with chronic eosinophilic pneumonia may inhibit EGPA development via the action of cytokines, such as IL-10 and TGF-β, which are produced by CD4+CD25+ cells, and IL-2, which is produced by CD4+CD25− T cells." (PMID 25174446, 2014). "Although there is no direct evidence yet for this hypothesis in asthma, in other contexts HLA-G has been shown to suppress dendritic cells and T cells that participate in inflammation, and to activate CD4+CD25+FoxP3+ regulatory T cells that can suppress cells that participate in airway inflammation." (PMID 23327606, 2013).
asthma (continued). "There was a significant positive correlation between IL15 expression and markers of T cells, including CD3E and CD8A but did not include CD4, suggesting the presence of nested CD8+ T cells in the airways of patients with asthma as previously observed." (PMID 40048261, 2025). "We then examined the individual subpopulations in these clusters; in CD4 cluster 16, we identified a significantly higher frequency of CD4+ CRTH2+ cells among T effector memory (TEM) and T central memory (TCM) cells in T2 groups with and without asthma." (PMID 40965120, 2025). "We found an increase in the percentage of CD8+, but not CD4+, TEMRAs in the peripheral blood (PB) and BAL cells of patients with SA, but not MMA, positively correlating with asthma symptom duration." (PMID 40048261, 2025). "In this study, we aimed to identify ILC, CD4+, and CD8+ T cell populations in blood that differentiate between T2 and non‐T2 features in subjects with and without asthma." (PMID 40965120, 2025). "Our observations revealed significantly increased expression of CD46 on CD4+ T cells from AEA patients, with prominent elevation in mild and moderate asthma regardless of the allergy season." (PMID 39403120, 2024). "Our results showed that C57BL/6 mice presented the highest lung levels of CD4+CD25+Foxp3+ cells in the presence or absence of allergen provocation and failed to develop asthma characteristic features following allergen provocation." (PMID 34924814, 2021). "Relevant to the human condition, DCN expression was also increased in CD4+ and CD8+ T cells from patients with non-steroid-dependent asthma relative to healthy controls (GSE31773)." (PMID 34880260, 2021). "The rate of the proliferation of CD4+ T cells significantly differed between the PBMC culture and P+S coculture in both the asthma (P < 0.0005) and nonasthma groups (P < 0.05)." (PMID 31673233, 2019). "This study evaluated the effect of placenta-derived MSCs on the activation and proliferation of CD4+ T cells and CD8+ T cells in children with and without asthma." (PMID 31673233, 2019). "The rate of the activation of CD4+ T cells significantly differed between the PBMC culture and P+S coculture in the asthma group (P < 0.0005) but not in the children without asthma." (PMID 31673233, 2019). "Whereas CD4+ T cell depletion completely aborted influx of eosinophils in the BAL, administration of the other antibodies did not inhibit asthma hallmarks." (PMID 29444897, 2018). "Compared with vehicle-treated mice with experimental asthma, AAL-R mildly reduced CD4+ T lymphocyte numbers in the MLNs and failed to modulate CD19+ B cell and DC numbers in this compartment." (PMID 25645346, 2015). "We did not observe a significant difference between asthma and controls with respect to the incidence of other Foxp3 or IL-10 positive cells: CD4+Foxp3+, CD4+Foxp3+CD25+, CD4+IL-10+IL-4- or CD4+Foxp3+IL-10+." (PMID 25132806, 2014). "On the other hand an increase in IL-10 and IL-13 in the CD4+, but not in the CD8+ T cells, was related with duration of asthma." (PMID 21197090, 2010). "The proportion of CD4+CD25+ (p = 0.20) and CD4+CD25+bright (p = 0.55) cells were similar between neonates with (n = 57) and without (n = 50) maternal asthma." (PMID 19586545, 2009). "While we noted no statistical differences in the frequencies and counts per milliliter of blood for total CD3+ T cells (data not shown), we did notice that CD4+ T cells were elevated in females with asthma compared to males, while CD8+ T cells were increased in males compared to females with asthma." (PMID 40821845, 2025). "Since we do not detect genotype-specific differences in mRNA degradation of IL-4 or IL-13 in polyclonally stimulated CD4+ T cells and no degradation of IL-5 mRNA, modulation of mRNA stability by KSRP does not appear to be the main reason for the effects observed in our asthma model." (PMID 40095032, 2025).